PTK6 (protein tyrosine kinase 6)
Description:
Non-receptor tyrosine-protein kinase implicated in the regulation of a variety of signaling pathways that control the differentiation and maintenance of normal epithelia, as well as tumor growth. Function seems to be context dependent and differ depending on cell type, as well as its intracellular localization. A number of potential nuclear and cytoplasmic substrates have been identified. These include the RNA-binding proteins: KHDRBS1/SAM68, KHDRBS2/SLM1, KHDRBS3/SLM2 and SFPQ/PSF; transcription factors: STAT3 and STAT5A/B and a variety of signaling molecules: ARHGAP35/p190RhoGAP, PXN/paxillin, BTK/ATK, STAP2/BKS. Phosphorylates the GTPase-activating protein ARAP1 following EGF stimulation which enhances EGFR signaling by delaying EGFR down-regulation. Also associates with a variety of proteins that are likely upstream of PTK6 in various signaling pathways, or for which PTK6 may play an adapter-like role. These proteins include ADAM15, EGFR, ERBB2, ERBB3 and IRS4. In normal or non-tumorigenic tissues, PTK6 promotes cellular differentiation and apoptosis. In tumors PTK6 contributes to cancer progression by sensitizing cells to mitogenic signals and enhancing proliferation, anchorage-independent survival and migration/invasion. Association with EGFR, ERBB2, ERBB3 may contribute to mammary tumor development and growth through enhancement of EGF-induced signaling via BTK/AKT and PI3 kinase. Contributes to migration and proliferation by contributing to EGF-mediated phosphorylation of ARHGAP35/p190RhoGAP, which promotes association with RASA1/p120RasGAP, inactivating RhoA while activating RAS. EGF stimulation resulted in phosphorylation of PNX/Paxillin by PTK6 and activation of RAC1 via CRK/CrKII, thereby promoting migration and invasion. PTK6 activates STAT3 and STAT5B to promote proliferation. Nuclear PTK6 may be important for regulating growth in normal epithelia, while cytoplasmic PTK6 might activate oncogenic signaling pathways. [Isoform 2]: Inhibits PTK6 phosphorylation and PTK6 association with other tyrosine-phosphorylated proteins.
Synonyms: BRK
Tractability: Small molecule: an approved drug acts on it; a structure with a bound ligand is known; a high-quality ligand is known; it belongs to a druggable protein family. Antibody: its Gene Ontology location is reachable by antibodies, with high confidence. PROTAC: it is named in the literature on targeted protein degradation; ubiquitination databases record sites on it; a small molecule that binds it is known.
Target class: Kinase; TK protein kinase group; Enzyme; Protein Kinase; Tyrosine protein kinase Src family
Chemical probes: Tilfrinib (high quality)
Gene: Protein-coding gene on chromosome 20 (63,528,001 to 63,537,376, reverse strand). Ensembl gene ENSG00000101213.
Subcellular location: Cytoplasm; Nucleus; Cell projection, ruffle; Membrane
Subcellular location (Human Protein Atlas): Nucleoplasm; Cytosol; Nuclear bodies; Plasma membrane
Pathways (Reactome):
Signal Transduction: ERBB2 Activates PTK6 Signaling; PTK6 Activates STAT3; PTK6 Down-Regulation; PTK6 Expression; PTK6 Regulates Cell Cycle; PTK6 Regulates Proteins Involved in RNA Processing; PTK6 Regulates RHO GTPases, RAS GTPase and MAP kinases; PTK6 Regulates RTKs and Their Effectors AKT1 and DOK1; PTK6 promotes HIF1A stabilization
Cell Cycle: Cyclin D associated events in G1; SCF(Skp2)-mediated degradation of p27/p21
Cellular responses to stimuli: Cytoprotection by HMOX1
Gene Ontology:
Molecular function: identical protein binding; non-membrane spanning protein tyrosine kinase activity; protein binding; protein tyrosine kinase activity; signaling receptor binding; ATP binding; protein kinase activity
Biological process: cell migration; cellular response to retinoic acid; negative regulation of protein tyrosine kinase activity; positive regulation of neuron projection development; protein autophosphorylation; tyrosine phosphorylation of STAT protein; cell differentiation; cell surface receptor protein tyrosine kinase signaling pathway; ERBB2 signaling pathway; positive regulation of cell cycle; positive regulation of DNA replication; positive regulation of epidermal growth factor receptor signaling pathway; positive regulation of receptor signaling pathway via JAK-STAT; protein phosphorylation; intestinal epithelial cell differentiation; negative regulation of growth
Cellular component: cytoplasm; cytosol; nuclear body; nucleoplasm; nucleus; ruffle; plasma membrane; membrane
Genetic constraint (gnomAD): Loss-of-function variants: 47 observed, 47.76 expected, observed/expected ratio (o/e) 0.98, 90% interval 0.78 to 1.25. The upper end of that interval is the gene's LOEUF score, 1.25, which puts it in group 5 of 6, group 1 being the genes least tolerant of losing a copy. Missense variants: 618 observed, 623.72 expected, observed/expected ratio (o/e) 0.99, 90% interval 0.93 to 1.06. Synonymous variants: 287 observed, 267.86 expected, observed/expected ratio (o/e) 1.07, 90% interval 0.97 to 1.18.
Cancer hallmarks: proliferative signalling (promotes); invasion and metastasis (promotes); suppression of growth (promotes); escaping programmed cell death (suppresses)
Homologues: Orthologues: chimpanzee PTK6 (99% identical), macaque PTK6 (96% identical), mouse Ptk6 (80% identical), pig PTK6 (80% identical), guinea pig PTK6 (80% identical), rat Ptk6 (80% identical), tropical clawed frog ptk6 (50% identical), zebrafish ptk6a (46% identical), zebrafish ptk6b (46% identical). Paralogues in human: SRC (45% identical), SRMS (45% identical), FRK (45% identical), FYN (44% identical), YES1 (44% identical), FGR (43% identical), HCK (42% identical), BLK (41% identical), LCK (41% identical), LYN (40% identical), ABL2 (38% identical), ABL1 (37% identical), and 20 more.
Diseases named in the same sentence as PTK6 in open-access papers:
PTK6 is named in the same sentence as 87 diseases in open-access papers, as found by Europe PMC text mining. Sharing a sentence is not in itself a finding about the gene and the disease. The quoted sentences say what the papers report.
breast carcinoma (59 papers, 2007 to 2025). "Breast tumor kinase (Brk/PTK6) was overexpressed in over 80% of breast cancers and is associated with poor patient outcomes.PTK6 protein expression is associated with different prognosis indifferent tumor types." (PMID 37932734, 2023). "In our analysis of ER+ breast cancer patients in The Cancer Genome Atlas, higher relative expression of PTK6 transcript is associated with poor overall survival." (PMID 29167821, 2017). "In contrast, studies in other types of cancer, including breast cancer and non-small cell lung cancer, showed that high PTK6 expression was significantly associated with low 5-year OS rates." (PMID 27311570, 2016). "PTK6 was also reported as positive associated to metastases-free survival in breast cancer; and shows strong cis CN/mRNA correlation in our analysis." (PMID 22860045, 2012). "Using immunohistochemistry on breast cancer tissues, PTK6 expression was shown to be associated with the expression of HER receptors, and with the course of the breast cancer disease." (PMID 20700126, 2010). "In multiple microarray studies, elevated PTK6 mRNA expression was most highly associated with specific breast cancer subtypes (Her2+ and Luminal B/high grade ER+)." (PMID 20668531, 2010). "In this study, we investigated the protein expression of the HER receptor family (HER1-HER4) and the cytoplasmic tyrosine kinase PTK6 in archival tissue from 193 breast carcinomas, and tested the association between markers and patient prognosis." (PMID 17299391, 2007). "PTK6 is a tyrosine kinase, which was previously associated with breast cancer progression and may therefore be a candidate biomarker for high-risk DCIS, as well as a potential therapeutic target." (PMID 37116492, 2023). "Indeed, mouse xenografts of breast cancer cells carrying a kinase-inactive PTK6 (due to K219M mutation) still developed into tumors at a similar rate to those with wildtype PTK6." (PMID 37509364, 2023). "To date, some of the most potent PTK6 inhibitors, causing significant repression of breast cancer cell migration and invasion, are marine natural products such as the derivatives of the marine Triterpene Sipholenols: 4β-O-benzyl sipholenol A and 4β-O-benzyl-19,20-anhydrosipholenol A." (PMID 37509364, 2023). "Additionally, STAT3, FAK, and BCAR1 are relevant PTK6 substrates in breast cancer, and PTK6 protects breast cancer cells from autophagic cell death induced by loss of anchorage, suggesting that PTK6 can inhibit autophagic processes." (PMID 33109128, 2020). "High transcriptional levels of PTK6 are associated with poor disease prognosis in breast cancers." (PMID 29879184, 2018). "The association of PTK6 with cancers is widely studied in breast cancers." (PMID 29879184, 2018). "Although several interaction partners of PTK6 have been identified in cellular cultures, and positive PTK6 expression in breast cancer tissue is associated with better prognosis survival, the function of PTK6 as well as its function in LSCC development and survival prognosis remained unclear." (PMID 23497344, 2013). "Effects of PTK6 on anchorage-independence could contribute to the poor outcomes associated with high PTK6 transcript levels that we found in multiple cohorts of breast cancer patients." (PMID 20668531, 2010). "PTK6 is overexpressedin breast cancer and deemed as an oncogene to promote cancer cell growth, survival, and migration." (PMID 40636215, 2025). "PTK6 has been thoroughly investigated in breast cancer, showing elevated expression in different subtypes such as ER-positive, ERBB2-positive, and triple-negative cancers." (PMID 40809015, 2025). "PTK6 was initially identified in cultured human melanocytes in 1993 and subsequently isolated and characterized in breast cancer and mouse intestinal epithelium." (PMID 40809015, 2025). "PTK6 is now the focus of research in prostate, colorectal, and particularly breast cancer, which is frequently highly expressed in tumor and associated with poor prognosis." (PMID 38573548, 2024).
breast carcinoma (continued). "PTK6 is activated and autophosphorylated in patient with breast cancers and breast cancer cell lines." (PMID 38457262, 2024). "PTK6 expression levels in breast cancer are correlated with a higher probability of tumor cell invasion, migration, and metastasis." (PMID 38573548, 2024). "PTK6 has been most widely studied in a variety of epithelial tumors, several studies indicate that knockdown PTK6 contribute to suppress breast cancer cell migration, invasion and metastasis." (PMID 38573548, 2024). "Recently the ratio of ALT-PTK6 to full-length PTK6 expression was shown to have significant prognostic value in predicting patient outcomes in breast cancer." (PMID 37509364, 2023). "Most of the studies to date on PTK6 and breast cancer have been based on animal models or celllines, with little validation carried out in tumor tissues from breast cancer patients." (PMID 37932734, 2023). "Kinase-inactive PTK6 was also shown to promote the proliferation of the T47D breast cancer cell line." (PMID 37509364, 2023). "Significant differences in expression are evident in breast cancer, with PTK6 expressed more highly in tumors than normal tissue as expected, but not in prostate cancer despite evidence suggesting the importance of PTK6." (PMID 37509364, 2023). "Up-regulation of PTK6 expression can promote the growth of ER + breast cancer cells, whereas down-regulation can induce cell apoptosis." (PMID 37932734, 2023). "PTK6 has long been known as a prognostic biomarker in breast cancer, but its importance in other cancers is less clear, and the available data are complex and sometimes conflicting." (PMID 37509364, 2023). "Protein tyrosine kinase 6 (PTK6) is a biomarker of poor prognosis in breast cancer, but its importance in other cancer types is unclear." (PMID 37509364, 2023). "PTK6 has also been found to induce tumor cell migration, invasion and metastasis in breast cancer, ovarian cancer, nasopharyngeal cancer, small cell lung cancer and prostate cancer." (PMID 37932734, 2023). "Significantly reduced phosphorylation of PTK6 and its substrates was observed, accompanied by reduced invasiveness and migration of breast cancer cells." (PMID 37509364, 2023). "Previous studies have indicated that the abnormal expression of PTK6 is related to a variety of malignant tumors, including breast cancer, hepatocellular carcinoma, esophageal squamous cell carcinoma, prostate cancer, and colorectal cancer." (PMID 36690663, 2023). "PTK6 expression has been shown to contribute to breast cancer cell migration, invasion and metastasis in many other studies." (PMID 37932734, 2023). "Another study presents PROTACs that target the degradation of protein tyrosine kinase 6 (PTK6), consisting of CRBN and VHL E3 ubiquitin ligase ligands and a published PTK6 inhibitor, as a potential treatment for breast cancer." (PMID 36142231, 2022). "PTK6 was first discovered in cultured human melanocytes, and then it was cloned and characterized in breast cancer and mouse intestinal epithelium." (PMID 36228719, 2022). "During the first phase of our investigation, a functional genomic screen aiming to locate regulators of anchorage-independent survival helped us zero in on PTK6 as a crucial mediator of anoikis resistance in breast cancer cells." (PMID 36405012, 2022). "Compared with a single PTK6 inhibitor, the compounds showed a better inhibitory effect on ER+ breast cancer cells and platinum-resistant ovarian cancer cells." (PMID 36142231, 2022). "PTK6 regulates insulin-like growth factor to enhance the anchorage-independent survival of breast cancer cells." (PMID 35562900, 2022). "In breast cancer, PTK6 has also been verified to play a critical role in epithelial–mesenchymal transition (EMT)." (PMID 35562900, 2022).
breast carcinoma (continued). "The analysis of the breast cancer scRNAseq dataset shows that PTK6 and SRC are highly expressed in cells from all cancer types (basal, cycling, HER2+, Luminal A, and Luminal B) with a high correlation between PTK6 and SRC expression in these cells." (PMID 36228719, 2022). "In one study, PTK6 inhibition led to an increase in apoptosis of lapatinib-resistant HER2+ breast cancer cell lines, while inhibition of SRC kinase by SRC kinase inhibitors restored lapatinib sensitivity, in a different study." (PMID 36228719, 2022). "It has been detected that PTK6 overexpression is correlate with the poor prognosis of bladder cancer, prostate cancer, and breast cancer." (PMID 33768004, 2021). "PTK6 promoted the proliferation, survival and metastasis of breast cancer, and also contributed to its resistance to targeted therapies." (PMID 34551797, 2021). "Expression of PTK6 is often found co-amplified with members of the EGF receptors including ERBB4 in breast cancer." (PMID 34136393, 2021). "PTK6 is highly expressed in multiple tumor types, including prostate, ovarian, and breast cancers, and participates in the regulation of tumor cell proliferation, migration, and survival." (PMID 31447885, 2019). "A growing body of evidence suggests oncogenic roles for PTK6 in breast cancers, and targeting its kinase activity by small molecule inhibitors has been proposed as a potential therapy for the treatment of breast cancers." (PMID 29879184, 2018). "Given the growing evidence for a critical role for PTK6 in breast cancer cell survival, we sought to determine the functional role of PTK6 in ER+ Luminal breast cancer cells." (PMID 29167821, 2017). "Based on these in silico results, we next investigated the role of PTK6 in promoting the growth of ER+ breast cancer cells, including those that are resistant to endocrine therapies." (PMID 29167821, 2017). "The researchers showed that this effect was dependent on the activation of a signaling pathway previously found to be important in another subtype of breast cancer, highlighting a conserved mechanism of cell survival regulation by PTK6." (PMID 29167821, 2017). "Enhanced expression of PTK6 in ER+ breast cancer cells enhances growth of ER+ breast cancer cells, including tamoxifen-treated cells." (PMID 29167821, 2017). "To further elucidate the functional role of PTK6 in ER+ breast cancer cells, we used two independent shRNA vectors (C9 or 49) to downregulate expression of PTK6 in ER+ cells." (PMID 29167821, 2017). "It is possible that PTK6 downregulation induces metabolic, oxidative or inflammatory stress in ER+ breast cancer cells, thereby activating p38 MAPK." (PMID 29167821, 2017). "A team led by Hanna Irie from the Icahn School of Medicine at Mount Sinai in New York, NY, USA, investigated the role of PTK6, also known as breast tumor kinase, in breast cancer cells that grow in response to the hormone estrogen." (PMID 29167821, 2017). "Our current study clearly highlights a critical role for PTK6 in the growth and survival of ER+ breast cancer cells, including those resistant to endocrine therapies." (PMID 29167821, 2017). "Based on these results, we conclude that PTK6 downregulation induces apoptosis and inhibits the in vitro and in vivo growth of ER+ breast cancer cells, including those resistant to endocrine therapies currently used in clinical practice." (PMID 29167821, 2017). "To determine if p38 activity is required for PTK6 shRNA-induced apoptosis of ER+ breast cancer cells, we treated PTK6 shRNA-expressing cells with SB203580, a p38 MAPK inhibitor." (PMID 29167821, 2017). "In conclusion, our studies elucidate critical functions of PTK6 in ER+ Luminal breast cancers and support PTK6 as an attractive therapeutic target for ER+ breast cancers." (PMID 29167821, 2017).